CENPE (centromere protein E)
Diseases named in the same sentence as CENPE in open-access papers (continued):
Sharing a sentence is not in itself a finding about the gene and the disease.
prostate carcinoma (9 papers, 2013 to 2025). A carcinoma that arises from epithelial cells of the prostate gland. "CENPE was aberrantly upregulated in multiple types of cancer and was associated with facilitated cell-cycle progression and tumor cell growth, such as in epithelial ovarian cancer, prostate cancer and triple-negative breast cancer." (PMID 30716092, 2019). "The alternative splicing of CENPE was also reported in prostate cancer cells upon CLK pharmacological inhibition by TG003, where the expression of exon 38 inclusion isoform significantly increased upon TG003 treatment." (PMID 40731028, 2025). "The progression of castration-resistant prostate cancer cells to G2-M phase is heavily dependent on CENPE." (PMID 30716092, 2019). "Moreover, Lysine‐Specific Demethylase 1 (LSD1)–mediated epigenetic reprogramming activates the transcription of CENPE, which in turn drives the progression of castration‐resistant prostate cancer." (PMID 40794013, 2025). "In prostate cancer, CENPE expression could be activated by LSD through binding to the promoter region." (PMID 34868981, 2021). "PCAT-1 is transcribed from chr8q24 and promotes prostate cancer cell proliferation by regulating target genes in trans, including BRCA2 (breast cancer early-onset 2), CENPF (centromere protein F) and CENPE (centromere protein E)." (PMID 23875687, 2013). "Consistent with reports in non‐small‐cell lung cancer, prostate cancer and triple‐negative breast cancer, we show that CENPE drives proliferation and invasion." (PMID 40794013, 2025). "Furthermore, relative to the non-castration-resistant prostate cancer cell line (LNCaP), the expression of KIF14, CENPE, KIF15, KIF18B, and KIFC1 was significantly elevated in the castration-resistant PCa cell line (DU145)." (PMID 40956849, 2025).
glioma (6 papers, 2011 to 2024). A benign or malignant brain and spinal cord tumor that arises from glial cells (astrocytes, oligodendrocytes, ependymal cells). "In pediatric high-grade glioma cell lines, CENPE knockdown, alone or in combination with TZM, reduces cell proliferation and induces cell cycle arrest." (PMID 34663805, 2021). "The analysis of four Affimetrix GeneChip datasets, comprising 771 glioma samples, revealed that CENPE expression correlates with WHO grade of glioma patients, with a higher expression in grade IV tumors." (PMID 34663805, 2021). "We demonstrated that miR-137 and miR-6500-3p exhibit anti-tumor activity in pediatric glioma cell lines by blocking CENPE, KIF14 or NCAPG expression." (PMID 26933822, 2016). "The result of immunohistochemistry for antibodies directed against seven of the SAC proteins in our study (all except CENPE) are available for 11 grade III/IV glioma and three normal brain cores in the HPA database." (PMID 22022424, 2011). "After calculating the hazard ratio and confidence interval, we observed that 8 hub genes in hub network 1 were related to the poor prognosis of gliomas, including PBK, KIF2C, CENPE, KIF14, MND1, FAM83D, NEIL3, and CDKN3." (PMID 35387222, 2022). "CENPE and KIF14 downregulation was shown to potentiate the effects of TZM in reducing glioma cell proliferation." (PMID 34663805, 2021). "Expression of six SAC genes, BUB1, BUB1B, CDC20, CENPE, MAD1L1 and TTK were found to be significantly positively correlated with WHO grades of glioma patients (p<0.01)." (PMID 22022424, 2011). "RNA levels of eight major mitotic spindle assembly checkpoint (SAC) genes (BUB1, BUB1B, BUB3, CENPE, MAD1L1, MAD2L1, CDC20, TTK) significantly correlated with glioma grade and six also significantly correlated with survival time." (PMID 22022424, 2011).
hepatocellular carcinoma (6 papers, 2009 to 2025). A malignant tumor that arises from hepatocytes. "consistently reported an association of CENPE with adverse clinical features of hepatocellular carcinoma." (PMID 40794013, 2025). "Furthermore, evidence illustrated reduced CENPE mRNA expression found in a human hepatocellular carcinoma (HepG2) versus a normal liver cell line (LO2); the results were further validated using western blot analysis and quantitative real-time PCR." (PMID 29618387, 2018).
esophageal cancer (5 papers, 2019 to 2024). A primary or metastatic malignant neoplasm involving the esophagus. "In this study, using data from the Cancer Genome Atlas-Esophageal Carcinoma (TCGA-ESCA), we analyzed the expression profile of CENPE mRNA in ESCC and EA, its independent prognostic value in terms of overall survival (OS) and the potential mechanisms of its dysregulation in EA." (PMID 30716092, 2019).
microcephaly (5 papers, 2015 to 2024). A congenital or acquired developmental disorder in which the circumference of the head is smaller than normal for the person's age and sex. "Researchers observed disorientation of cell division in the cells of patients with CENPE mutations in microcephaly, and our genetic perturbation findings provide additional insight into how microcephaly is caused by centrosome defects." (PMID 38353329, 2024). "Neural progenitors are strongly sensitive to CENPE levels, because microcephaly is a haplo-insufficient phenotype of CENPE loss." (PMID 33804489, 2021). "Since CENP-E was first identified as a component of the kinetochore involved in chromosome alignment, it was anticipated that the mutations in CENPE provoke microcephaly through defects in chromosome segregation." (PMID 33742057, 2021). "Also, centromere-associated protein E (CENPE), the gene coding for centromere-associated protein E was found mutated in patients with microcephalic primordial dwarfism (MPD), featuring microcephaly and a simplified gyral pattern (OMIM 616051)." (PMID 25729350, 2015).
neuroblastoma (5 papers, 2015 to 2023). Neuroblastoma (NB) is the most common solid, extracranial childhood tumor. "Interestingly, neuroblastoma cell lines have been shown to be sensitive to depletion of Centrosome-associated protein E (CENPE), a prometaphase protein required for establishment and maintenance of kinetochores and spindle microtubule connections." (PMID 28602975, 2017). "However, the CENPE inhibitor GSK923295 was effective against a broad spectrum of neuroblastoma cell lines." (PMID 28602975, 2017).
lymphoma (4 papers, 2016 to 2025). A malignant (clonal) proliferation of B- lymphocytes or T- lymphocytes which involves the lymph nodes, bone marrow and/or extranodal sites. "Previous research has shown that the downregulation of CENPE causes an increase in aneuploidy, which in turn triggers an elevated level of spontaneous lymphomas and lung tumors in aged animals, implying that CENPE acts as a tumor suppressor." (PMID 35496042, 2022).
non-small cell lung carcinoma (4 papers, 2020 to 2023). A group of at least three distinct histological types of lung cancer, including non-small cell squamous cell carcinoma, adenocarcinoma, and large cell carcinoma. "CENPE had been regarded as a potential biomarker of diverse cancers, such as invasive ductal carcinoma and non-small cell lung cancer." (PMID 37925501, 2023). "In a research of 1,195 non-small cell lung cancer (NSCLC) patients’ samples, CENPE was revealed to be highly expressed and patients with strong CENPE expression had a relatively low overall survival rate." (PMID 34868981, 2021). "Thus, we first examined the expression of CENPE and MPS-1 in A549 and NCI-H460 non-small cell lung cancer (NSCLC) cell lines." (PMID 38258067, 2023).
sarcoma (4 papers, 2019 to 2022). A usually aggressive malignant neoplasm of the soft tissue or bone. "Perticurlarly for CENPE, it can be used as a novel target for sarcoma diagnosis and prognosis." (PMID 34485383, 2021). "As prior work already has validated asparagine starvation as an actionable metabolic vulnerability in sarcomas, this study concentrates on the potential roles of UBE2C, CENPE, HAS2 and CREB3L2 in STS with a focus on RMS." (PMID 32898143, 2020). "Increased expression of UBE2C, CENPE and CREB3L2 compared to normal muscle was detected in 9 of 9 human sarcoma cell lines analyzed, whereas HAS2 expression was detected in only 5 of 9 human sarcoma lines." (PMID 32898143, 2020). "Amongst the eight remaining hub genes, CDC20, CCNB2, AURKB, MAD2L1, CENPE, KIF2C, and PCNA were highly expressed and related with negative prognosis of sarcoma." (PMID 31870357, 2019).
clear cell renal cell carcinoma (3 papers, 2020 to 2025). "However, the expression pattern, biological roles, and underlying molecular mechanism of CENPE in clear cell renal cell carcinoma (ccRCC) progression have not been fully elucidated." (PMID 40794013, 2025).
esophageal adenocarcinoma (3 papers, 2019 to 2021). A malignant tumor with glandular differentiation arising predominantly from Barrett mucosa in the lower third of the esophagus. "Recent study found that CENPE expression is associated with its DNA methylation status in esophageal adenocarcinoma." (PMID 34745136, 2021).
gastric cancer (3 papers, 2020 to 2024). A primary or metastatic malignant neoplasm involving the stomach. "Our study confirms that CENPE is highly expressed in gastric cancer and correlates with the prognosis of gastric cancer patients, which provides a basis for the diagnosis and prognosis of gastric cancer." (PMID 38702677, 2024). "It was shown that patients with gastric cancer who expressed high levels of CENPE had a lower overall survival (OS) compared to those who had low levels of CENPE." (PMID 38702677, 2024). "CENPE expression also correlated with immune-infiltrating cells in the gastric cancer microenvironment and was positively connected to NK cells and mast cells." (PMID 38702677, 2024). "The purpose of this study was to explore the effect and clinical significance of CENPE in gastric cancer." (PMID 38702677, 2024). "Multiple public databases were then used to explore the expression, prognosis, biological function, and related signal pathways of CENPE in gastric cancer." (PMID 38702677, 2024). "In line with the findings of the GEPIA, real-time fluorescence quantitative PCR (qPT-PCR) confirmed that CENPE was overexpressed in gastric cancer cells." (PMID 38702677, 2024). "The gene expression profiling interaction analysis (GEPIA) was used to evaluate the relationship between prognosis and CENPE expression in gastric cancer patients." (PMID 38702677, 2024). "According to immunohistochemical examination, paracancerous tissues had minimal expression of CENPE, but gastric cancer showed significant expression of the protein." (PMID 38702677, 2024). "According to the analysis of the GEPIA database, the expression of CENPE is increased in gastric cancer tissues compared to normal tissues." (PMID 38702677, 2024). "We used GSEA to explore the mechanism of CENPE in gastric cancer." (PMID 38702677, 2024). "Therefore, in this study, samples related to gastric cancer were obtained from TCGA and GEO databases, and the differential gene CENPE was identified through a joint screening process." (PMID 38702677, 2024). "We further demonstrate the significant expression of CENPE in gastric cancer using real-time fluorescence quantitative PCR and immunohistological analysis, indicating that CENPE may promote the development of GC." (PMID 38702677, 2024). "CENPE might be a target for gastric cancer therapy and a predictor of a bad prognosis." (PMID 38702677, 2024). "Many previous studies have reported a high expression level of centromere protein E (CENP-E) and centromere protein W (CENP-W) in several solid tumors such as uterine cervical cancer, gastric cancer, and hypopharyngeal cancer." (PMID 33833984, 2021).
acute lymphoblastic leukemia (2 papers, 2021 to 2024). Leukemia with an acute onset, characterized by the presence of lymphoblasts in the bone marrow and the peripheral blood. "Moreover, an anti-mitogenic agent GSK923295A, capable of inhibiting CENPE motility activity, exhibited substantial remission-inducing antileukemia activities towards acute lymphoblastic leukemia (ALL) xenografts." (PMID 34868981, 2021).
autoimmune disease (2 papers, 2021 to 2023). A disorder resulting from loss of function or tissue destruction of an organ or multiple organs, arising from humoral or cellular immune responses of the individual to their own tissue constituents. "Interestingly, the lead SNP at the MANBA/UBE2D3 locus, rs223486, is an intergenic variant located in a region (±500 kb) that harbors several other genes (CISD2, NFKB1, SLC9B1/2, BDH2 and CENPE) with reported inflammatory and autoimmune disease associations." (PMID 33402679, 2021). "However, some studies have shown that abnormal expression of CENPE can also exist in some autoimmune diseases." (PMID 37335738, 2023).
brain tumor (2 papers, 2021 to 2025). "Of potential interest in this context, CENPE has been suggested as a target for cancer therapy in high-grade brain tumors as a less toxic alternative to microtubule poisons that are effective but cause severe side effects." (PMID 39995872, 2025). "In conclusion, inhibition of KNL1, CENPE, ASPM, CITK, and KIF14 may mimic the effects of MTAs on cell division but could work with particular effectiveness on brain tumor cells, underscoring the importance of developing specific inhibitors and test them in clinical trials." (PMID 34663805, 2021).
COVID-19 (2 papers, 2023 to 2025). A disease caused by infection with severe acute respiratory syndrome coronavirus 2. "We screened for statistically significant hub genes and found that ACTB was in low expression of both BD and COVID-19, and ASPM, CCNA2, CCNB1, and CENPE were in low expression of BD and high expression of COVID-19." (PMID 37335738, 2023). "Among the ten candidate hub genes, we found that 8 hub genes were differentially upregulated in HBV and COVID-19, so we further narrowed the scope of the study to 8 hub genes, including CDK1, E2F7, E2F8, TYMS, KIF20A, CENPE, TPX2, HMMR." (PMID 40408617, 2025). "In the context of COVID-19, studies have reported the impact of SARS-CoV-2 on mitotic processes, suggesting a potential link between CENPE activity and viral replication or host immune response." (PMID 40408617, 2025). "It has also been found that FOXM1 was highly expressed in the lungs of COVID-19 patients, which also suggests that co-expression of FOXM1 with CENPE may have an important impact on the regulatory process of viral replication and spread." (PMID 37335738, 2023).
Fanconi anemia (2 papers, 2021 to 2023). Fanconi anemia (FA) is a hereditary DNA repair disorder characterized by progressive pancytopenia with bone marrow failure, variable congenital malformations and predisposition to develop hematological or solid tumors.
infertile (2 papers, 2022 to 2025). "We finally found that CCNA2 and CENPE were related to infertile endometriosis." (PMID 40772274, 2025).
leukemia (2 papers, 2021). A malignant (clonal) hematologic disorder, involving hematopoietic stem cells and characterized by the presence of primitive or atypical myeloid or lymphoid cells in the bone marrow and the blood. "In leukemia, GSK923295A, which inhibited CENPE motility activity, exhibited significant remission induced anti-leukemia effect in the ALL xenografts." (PMID 34868981, 2021). "Because RUNX1 shRNA-treated THP-1 cells also showed impaired differentiation potentials, we questioned whether CENPE could further rescue leukemia cell differentiation ability." (PMID 34434964, 2021). "Since CENPE is a centrosome-associated protein that contributes to cell proliferation, we questioned whether RUNX1 regulated leukemia cell growth through CENPE." (PMID 34434964, 2021).
liver cancer (2 papers, 2023 to 2024). An epithelial or non-epithelial malignant neoplasm that arises from the liver. "One study using human hepatoma cell lines, animal models, and human liver cancer samples found that the low expression of CENPE contributes to the development of HCC, which is inconsistent with this study." (PMID 36894886, 2023).
Primary microcephaly (2 papers, 2023 to 2025). Head circumference below 2 standard deviations below the mean for age and gender at birth. "Defects in CENPE can lead to abnormal division of NPCs during development, identified previously as pathogenic in primary microcephaly." (PMID 40608414, 2025). "In research on the nervous system, it has been found that that as a key gene in primary microcephaly (MCPH) syndrome, CENPE mutations can lead to a decrease in brain capacity." (PMID 37593739, 2023).
retinoblastoma (2 papers, 2024). A malignant tumor that originates in the nuclear layer of the retina. "Centromere protein E (CENPE) is highly expressed in human tumors, and its mRNA and protein levels in retinoblastoma cells are also significantly upregulated." (PMID 38920989, 2024).
triple-negative breast carcinoma (2 papers, 2016 to 2019). An invasive breast carcinoma which is negative for expression of estrogen receptor (ER), progesterone receptor (PR), and human epidermal growth factor receptor 2 (HER2). "For example, in triple-negative breast cancer cells, CENPE expression was upregulated after Docetaxel treatment." (PMID 30716092, 2019). "It was a candidate gene for triple-negative breast cancer, and played a crucial role in suppressing tumorigenesis Depletion of CENPE resulted in promoting the Drosophila epithelial tissues overgrowth." (PMID 28030618, 2016).
adenoma (1 paper, 2013). A neoplasm arising from the epithelium. "Some genes or gene families we found up-regulated in MENX adenomas had previously been identified in human aggressive-invasive PAs, e.g., PTTG1, RACGAP1, CCNB1, CENPE, AURKB." (PMID 23756599, 2013).
B‐cell lymphoma (1 paper, 2025). "CENPE expression was also downregulated following DDR1 activation in two B‐cell lymphoma lines and was lost in most DDR1‐expressing primary tumours." (PMID 40401507, 2025). "We validated an antibody specific for CENPE protein and used this to show that CENPE protein levels were decreased by collagen treatment of the DDR1‐expressing B‐cell lymphoma lines and by expression of a constitutively activated DDR1 construct." (PMID 40401507, 2025). "We used RT‐qPCR to confirm the decreased expression of CENPE mRNA in collagen‐treated DDR1‐expressing GC B cells and B‐cell lymphoma lines." (PMID 40401507, 2025). "The kinesin motor protein, CENPE, was downregulated following DDR1 activation in both untransformed GC B cells and B‐cell lymphoma lines." (PMID 40401507, 2025).
endometriosis (1 paper, 2025). The growth of functional endometrial tissue in anatomic sites outside the uterine body. "Our study has identified eight potential mitosis hub genes (KIF4A, BUB1B, NEK2, FBXO5, KIF11, CENPE, CCNA2, and NCAPG) that exhibit excellent diagnostic properties for endometriosis." (PMID 40772274, 2025). "Then, we identified 11 potential mitosis-related downregulated hub genes, among which eight genes (KIF4A, BUB1B, NEK2, FBXO5, KIF11, CENPE, CCNA2, and NCAPG) showed good diagnostic properties of endometriosis and two genes (CCNA2, CENPE) were closely related to infertile endometriosis." (PMID 40772274, 2025). "We used the GSE25628 dataset to detect the expression of selected target genes, and the results showed that the differential expression of eight MRHGs (KIF4A, BUB1B, NEK2, FBXO5, KIF11, CENPE, CCNA2, and NCAPG) between control and endometriosis patients was consistent with predictions." (PMID 40772274, 2025).